STAT5A (signal transducer and activator of transcription 5A)
Diseases named in the same sentence as STAT5A in open-access papers (continued):
Sharing a sentence is not in itself a finding about the gene and the disease.
cancer (continued). "STAT5a plays a vital role in the promotion of cancers, including lung cancer, prostate cancer, and gastric cancer; is involved in chemoresistance in esophageal cancer by negatively regulating miR-29c; and is overexpressed in gemcitabine-resistant pancreatic cancer cell lines." (PMID 34336684, 2021). "In summary, genes including the HLA gene family, B2M, IRF4, and STAT5A might be the key genes involved in the anticolon cancer response of CD8+ T cells via regulation of cholesterol metabolism." (PMID 34858500, 2021). "Compatible with previous reports that miR‐23a influenced glucose metabolism in cancers, we observed that over‐STAT5A could importantly restrict glucose metabolism especially the glycolysis using stable isotope‐labeled [U‐13C6] glucose tracking." (PMID 33155364, 2021). "STAT3, STAT5A and STAT5B have been implicated in several physiological and disease processes such as cell division, migration, survival, cellular responses to pathogens, breast development, inflammation and cancer." (PMID 31443474, 2019). "Collectively, these findings indicate that Stat5a/b may provide a robust biomarker for recurrence of lethal PC after failure of first-line therapy for early stage cancer, warranting further investigation." (PMID 27741508, 2017). "Although STAT5a and STAT5b play a fundamental role in normal growth and development of the mammary gland, both proteins are overexpressed or constitutively activated in cancers, including some breast cancer tumors." (PMID 17997837, 2007). "Furthermore, functional assays could be employed to evaluate the biological consequences of NF-Y and STAT5A knockdown on cell behavior, including changes in proliferation, migration, and invasion capabilities of cancer cells." (PMID 38730626, 2024). "Based on the synergy between TET2 to IL-2/STAT5A signaling, we further examined whether VC enhanced the efficacy of anti-PD-L1 and IL-2 combination therapy, which is a potentially promising candidate for cancer therapy." (PMID 38177099, 2024). "Thus, the 22-month survival benefit of these constructs/anti-PD-L1/STAT5A/5B could be superior to the standard of cancer care." (PMID 39123391, 2024). "However, the prognostic role of STAT5a is dependent on cancer type." (PMID 37369132, 2023). "However, the role of STAT5a in cancer remains controversial." (PMID 37369132, 2023). "Thus, in the light of all these evidences suggesting that STAT3 and STAT5A play critical roles in cancer progression, the present study investigated the nature and extent of the involvement of STAT3 and STAT5A in the therapeutic response and disease progression of patients with GBM." (PMID 31783691, 2019). "Therefore, O-GlcNAc is a highly interesting and versatile PTM that could be an attractive target for new anti-cancer drug development, particularly in the context of oncogenic STAT5A in hematopoietic cancers." (PMID 30818760, 2019). "In particular, STAT5, which exists as two closely related isoforms, STAT5A and STAT5B, has emerged as a critical player in cancer biology, exhibiting complex and context-dependent functions that remain incompletely understood." (PMID 41301421, 2025). "In the cancer pathway, five genes (WNT1, DLL, TRAF1, GST, and GADD45) were upregulated, while CASP3, IKBKA, STAT5A, RPS6KA5, BIRC5, BIRC2/3, and SKP2 were downregulated." (PMID 40723320, 2025). "For example, responsible genes in the regulation of cancer cell survival and proliferation such as STAT1, STAT5A, CD44 and BCL2 are upregulated." (PMID 39056676, 2024). "STAT3 and STAT5A as well as STAT5B have pleiotropic roles in the body and can act as critical oncogenes that promote many processes involved in cancer development." (PMID 35229974, 2022). "The gene of STAT genes was altered in 1,003 (9%) samples; STAT1, STAT2, STAT3, STAT4, STAT5A, STAT5B, andSTAT6 were altered in 2.3%, 1.7%, 2.0%, 2.4%, 1.6%, 1.9%, and 1.9% of the demanded pan-cancer samples." (PMID 36176415, 2022).
cancer (continued). "Due to the increased activation of their stimulators, STATs are commonly constitutively active in disease and elevated activation of STAT3, STAT5A, STAT5B and in some cases STAT1, has been observed in most cancer types." (PMID 32915198, 2020). "To further our mechanistic knowledge of the pro-invasive role of STAT5a, we assessed the levels of pro-MMP-9, a pro-enzyme that facilitates degradation and proteolysis of the extracellular matrix to promote cancer cell dissemination and metastasis." (PMID 32633727, 2020). "It was found that preventing the expression of STAT3, STAT5A and STAT5B is related to the enhanced apoptosis in cancer cells." (PMID 31569687, 2019). "In fact, it has been observed that the modulation of c-Jun or Stat5a activation also modulates TNF shedding elicited by BPA and NP in cancer cell lines." (PMID 30065191, 2018). "Mechanistically, Stat5a/b regulation of both EMT and cancer stem-like cell properties were found to be mediated by Twist1, a well-characterized EMT transcription factor." (PMID 27741508, 2017). "Despite this gene has not been annotated to be related to oral cancer in GeneCards, both STAT5A and STAT5B belong to the STAT5 family the aberrant activity of which has been found to be related to various cancers." (PMID 26064958, 2015). "The new identification of these genes regulated by STAT5A and/or STAT5B has major implications for understanding the pathophysiology of cancer progression, neural disorders, and immune abnormalities." (PMID 24497979, 2014). "Our result are in accordance with observations of other investigators who have also reported STAT5A and STAT5B overexpression on mRNA and/or protein level in cancer tissue – prostate, breast, colorectal, esophageal and lung – when compared to normal tissue." (PMID 25137041, 2014). "The elucidation of the roles of STAT5A and STAT5B furthers our understanding of potential mechanisms in cancer pathophysiology, neural disorders, and abnormal T cell immune function providing potential new targets to study in these diseases." (PMID 24497979, 2014). "A study demonstrated that the nuclear EGFR can cooperate with STAT5A to target the promoter region of AURORA-A and enhance its expression in cancer cells." (PMID 21865609, 2011). "Many of the transcription factors with indirect effects, including PPARG, E2F1, STAT5A, and MYC, have been suggested as targets for cancer therapy." (PMID 18358079, 2008). "The pathway enriched in “Pathways in Cancer” with 15 genes, including ITGB1, STAT5A, and EGF." (PMID 40621499, 2025). "“Pathways in cancer” pathway, represented by genes ITGB1, STAT5A, and EGF." (PMID 40621499, 2025). "However, the function of STAT5A and B in promoting healing during IBD disease and cancer is not fully understood." (PMID 39136000, 2024). "STAT5A signaling, CSPG4, MMP-1, MMP-3, MMP-8, MMP-9, and LUM are all involved in cancer cell migration, invasion, and metastasis, while PKM supports the growth and survival of cancer cells by favoring aerobic glycolysis." (PMID 39201614, 2024). "Interestingly, signal transducer and activator of transcription 5A (STAT5A), a key protein in the JAK/STAT signaling pathway involved in various hematological malignancies and solid tumors, was upregulated in the NER compartment." (PMID 39677520, 2024). "In addition, the distribution of STAT1, STAT2, STAT3, STAT4, STAT5A, STAT5B, and STAT6 expression in CD8+ T cells in pan-cancer were displayed, which presented that STAT1 and STAT2 had prominent up-regulation in CD8+ T cell with ISG IFIT1." (PMID 36968603, 2023). "In addition, the gene expression levels of STAT5A and STAT5B were found to be organ specific and were significantly higher in cancer cells derived from lymphoid and myeloid organs." (PMID 35186733, 2022).
cancer (continued). "EGFR, KIT, MET, PPARG, and STAT5A were enriched in the Pathways in cancer, CAV1, EGFR, and MET were enriched in the Proteoglycans in cancer, and MET and PPARG were enriched in the Transcriptional misregulation in cancer." (PMID 35063044, 2022). "As presented here, the roles for the serine residues of STAT5a are nonredundant, exhibiting different effects on cancer characteristics, and different regulatory roles on the canonical pathway of PRL/STAT5a signaling." (PMID 34188118, 2021). "Although our study demonstrates STAT5a as a key factor during DCIS formation in vivo and which also stimulates pro-invasive properties in a DCIS model in vitro, more studies will be warented to fully undertand its biological role in early cancer progression." (PMID 32633727, 2020). "However, evidence suggests STAT5A and STAT5B play different functional roles in normal and cancer cell systems." (PMID 31684144, 2019). "One of the cancer cases treated with only radiation therapy showed diffuse and multifocal positivity for STAT3 and 2 cases that were treated with radiation therapy were diffuse and strongly positive for STAT5A." (PMID 29156772, 2017). "However, to promote cancer activity, they also target different genes including C/EBPβ, FOXO1, NFI-A, STAT5A, ARTN, FBXW7, and SEPT6 (for miR-223) and FUS1, RhoC, PTEN, CDKN1A, TGFβR2, and NRF2 (for miR-93)." (PMID 26273679, 2015). "Interestingly, it is known that STAT5A and STAT5B isoforms have distinct biological functions and the expression patterns of these proteins differ among many types of cancers cells." (PMID 25137041, 2014). "Although the STAT5A pathway has been well-known for promoting cell proliferation, invasion and survival in various cancers, it has not been shown whether and how this pathway is also involved in the regulation of NE trans-differentiation." (PMID 38745318, 2024). "Additionally, the distribution of STAT1, STAT2, STAT3, STAT4, STAT5A, STAT5B, and STAT6 expression in CD4+ T cells in pan-cancer were also clearly illustrated, which showed that STAT1 and STAT2 expression were notably up-regulated in CD4+ Treg cell with marker OSA1 and CD4+ T cell with ISG IFIT1." (PMID 36968603, 2023). "Based on these results, we speculate that genes including the HLA gene family, B2M, IRF4, and STAT5A that may be involved in EBV infection and cell adhesion molecule pathways play important roles in the anticolon cancer response of CD8+ T cells by regulating cholesterol metabolism." (PMID 34858500, 2021). "Together our results indicate a possible implication of STAT5a in estrogen-stimulated DCIS progression, a phenomenon that could be initiated by a decrease in stromal Cav-1 in vivo, and this possibility will also be tested in future studies with co-cultures with cancer fibroblasts." (PMID 32633727, 2020). "Although datasetA and datasetB were baseline nonmetastatic cancers that had not undergone ICI therapy, we still observed obvious similarities in spatial distribution patterns across ADGRE5, IL32 and STAT5A/B." (PMID 38343549, 2024). "Since there are almost no reports on the correlation between the CCDC71L gene and cancer in the published literature, we conducted RT-qPCR to detect the expression of 8 other potential downstream genes following STAT5A overexpression in AGS cells or STAT5A interference in SGC-7901 cells." (PMID 38879589, 2024).
infection (13 papers, 2011 to 2025). The state of being infected such as from the introduction of a foreign agent such as serum, vaccine, antigenic substance or organism. "Moreover, Stat5b-deficient cell lines grew out with a delay of ~12 weeks post infection, whereas Stat5a-deficient cells required about 6 weeks to form a stable cell line similar to wt lines, which succeeded to 100% to grow into stable cell lines (12/12)." (PMID 30679796, 2019). "Interestingly, EBV upregulated STAT3 and STAT5A levels, in particular between days 4 and 21 post-infection, whereas STAT5B levels were relatively constant." (PMID 38683861, 2024). "The majority of genes (CTNNB1, MARCO, STAT5a/b, TAP1, and TAP2) that regulate proliferation and differentiation of immune cells showed a differential higher expression in KO and SP-A variants in response to infection." (PMID 32670284, 2020). "Data indicated that CRNG significantly increase KITLG, FOXP3 and miR-451, and decrease ANPEP and STAT5A mRNA expression, suggesting that CRNG may be necessary for the modulation of antiviral immunity, inflammation and pathogen infection." (PMID 31178726, 2019). "Notably, STAT5A is known to promote expression of the anti-apoptotic gene BCL2, which was also present among the filtered KEGG gene list, suggesting a potential mechanism for increased cell survival during infection." (PMID 41356367, 2025). "Moreover, microarray assay in combination with CRNG interference and overexpression showed that the differential genes such as ANPEP, KITLG, STAT5A, FOXP3, miR-451, IL-2, IL-10, IL-6, and TNF-α are mainly involved in viral and pathogens infection and the immune-inflammatory responses in PK-15 cells." (PMID 31178726, 2019). "Surprisingly, in our study we also observed that more than 18 key genes, including Jak2, Stat3, Stat5a, Pik3r5 and Cish, of JAK-STAT pathway were significantly up-regulated by S. aureus + PG infection, thus indicating that S. aureus + PG treatment might also activate JAK-STAT signaling." (PMID 29304086, 2018). "Interestingly, the increased expression of ESE-1, STAT5A, AHRNT, LBP coupled with decreased expression of C/EBPα indirectly suggests that microbial translocation is occurring early in infection even though data from peripheral blood show modest evidence of elevated LPS in circulation." (PMID 22511950, 2012). "Moreover, STAT5A and PRDM1, two key regulators of Tfh cell development, were not upregulated under HIVYu2b infection in memPD-1pos-derived TfhD3." (PMID 34984326, 2022).
hematopoietic cancers (7 papers, 2019 to 2025). "Collectively, these data would undoubtedly define STAT3 and STAT5A/5B as important therapeutic targets in hematologic cancers." (PMID 31963765, 2020). "STAT5A/B are deregulated in a variety of hematopoietic and non-hematopoietic tumors." (PMID 31690038, 2019). "STAT5A/B signaling is enhanced in diverse hematopoietic cancers and is believed to drive disease." (PMID 31690038, 2019). "As mutations in STAT5B, but not STAT5A, have been frequently described in hematopoietic tumors, we used BCR/ABL as model systems to investigate the contribution of STAT5A or STAT5B for leukemogenesis." (PMID 30679796, 2019). "STAT3 and the two closely related STAT5A and STAT5B proteins are key players in the development of solid and haematopoietic cancers." (PMID 32667731, 2020).
immune disease (3 papers, 2019 to 2025). "Promoter hypermethylation of STAT5A, STAT5B, or SOCS1/3 genes has been implicated in the silencing of pathway modulators in various cancers and immune disorders." (PMID 41438753, 2025).
kidney disease (2 papers, 2016 to 2023). "Not surprisingly, there was a marked accumulation of CD44high IL-7Rαlow effector/memory T cells in Stat5b-deficient mice which, as with the incidence of kidney disease, was more pronounced in those bearing one-allele of Stat5a than in those bearing two." (PMID 26999798, 2016). "Although AOPEP has not been shown to be associated with kidney diseases, MIR2278 (microRNA 2278) can target STAT5A, which has been reported to contribute to the pathogenesis of kidney disease." (PMID 37386009, 2023).
blood cancer (1 paper, 2024). "Firstly, we incubated the STAT5A-iMac cells or control iMac cells with blood cancer cell K562 and solid tumor cell HO8910." (PMID 39872864, 2024).
cardiovascular diseases (1 paper, 2022). "As a signal transducer and transcriptional factor (TF), the role of STAT5A in theprogression of cardiovascular diseases remains contradictory." (PMID 37101540, 2022).
gastrointestinal tumors (1 paper, 2024). "First, we used other GEO database (GSE162004, GSE120860) to improve that STAT5A methylation in gastrointestinal tumors." (PMID 37256443, 2024). "For the downstream of YTHDF2, we used GEO databases to identify the STAT5A in gastrointestinal tumors." (PMID 37256443, 2024).
neurodevelopmental disorder (1 paper, 2014). A behavioral and cognitive disorder with onset during the developmental period that involves impaired or aberrant development of intellectual, motor, or social functions. "One might therefore speculate that STAT5A mutations may be lethal in humans, or that they may be involved in neurodevelopmental disorders that have yet to be associated with STAT5A dysfunction." (PMID 24497979, 2014).
STAT5A also shares sentences with these, for which no sentence is quoted: hepatocellular carcinoma (7 papers); head and neck squamous cell carcinoma (4); myocardial ischemia (3); cholangiocarcinoma (2); endometrial carcinoma (2); hematologic malignancies (2); inflammatory bowel disease (2); lymphopenia (2); metastatic tumor (2); neurodegenerative disease (2); oral squamous cell carcinoma (2); triple-negative breast carcinoma (2); adrenocortical tumors (1); anaplastic astrocytoma (1); Anxiety (1); astrocytoma (1); B-cell acute lymphoblastic leukemia (1); bladder urothelial carcinoma (1); bronchiectasis (1); carcinoma in situ (1); cardiac diseases (1); cardiac hypertrophy (1); Cerebral ischemia (1); cervical tumor (1); chronic eosinophilic leukemia (1); chronic lymphocytic leukemia (1); clostridium difficile infection (1); diffuse large B-cell lymphoma (1); eosinophilia (1); fibrosarcoma (1).
A further 45 diseases each share a sentence with STAT5A in 1 paper.